MMP9 (matrix metallopeptidase 9)
Diseases named in the same sentence as MMP9 in open-access papers (continued):
Sharing a sentence is not in itself a finding about the gene and the disease.
glioma (continued). "Hyperbaric oxygen therapy (HBOT) could inhibit glioma cell proliferation and inflammatory cell infiltration, and exert a sensitizing effect on ACNU therapy partially through enhancing oxygen pressure (PO2) in tumor tissues and lower expression levels of HIF‐1α, TNF‐α, IL‐1β, VEGF, MMP9, and NF‐κB." (PMID 27734611, 2016). "The results showed that when used individually, MMP9 and MUC4 tissue expression can predict clinical outcome in glioma patient diagnosis, which is not the case with EGFR." (PMID 36400876, 2022). "MMP9 and MUC4, but not EGFR, protein expression is correlated with increased glioma histological grades and IDH-WT genotype." (PMID 36400876, 2022). "MMP2 and, to a lesser extent, MMP9 were predictive of response, PFS, and OS in two independent small cohorts of patients with recurrent high-grade gliomas treated with bevacizumab, but not in a third cohort of patients treated by chemotherapy only." (PMID 34980260, 2022). "These include skin, decidual cells of the placenta, nucleus pulposus tissue of intervertebral disc, and MMP2 of glioma; however, it has not been documented on reduced MMP2 or MMP9 activity, reversed in response to the cytokines signal." (PMID 25774514, 2015). "Because the levels of vWF, MMP9, VCAM1, angiogenin, and HGF were increased in both GBM and MI patients, but not in the lower-grade gliomas, these factors seem to be necessary for neovascularization in general, both under reactive and high-grade neoplastic conditions." (PMID 31428150, 2019). "Moreover NFAT1, COX-2, MMP-7 and MMP-9 were simultaneously highly expressed in GBM, but not in low-grade gliomas." (PMID 23762456, 2013). "Besides, though MMP-9, EGFR, GST-π, and TOPO II all play crucial roles in the progression, invasion, migration and dissemination of gliomas, their expression levels do not differed among divergent recurrence groups, indicating that the recurrence pattern may not be determined by these molecules." (PMID 33585189, 2020).
melanoma (424 papers, 1999 to 2026). A malignant, usually aggressive tumor composed of atypical, neoplastic melanocytes. "It has been demonstrated that the intragenic hypermethylation of the MMP-9 gene in melanoma is linked to MMP-9 expression." (PMID 40563423, 2025). "CD93 deficiency in melanoma-bearing mice was associated with reduced endothelial barrier function in the primary tumor, enhanced expression of MMP9, and increased metastatic spread, which was reversed to wild-type levels when VEGFR2 signaling was inhibited." (PMID 38441970, 2024). "Elevated levels of MMPs, such as MMP-2 and MMP-9, are commonly observed in melanoma and are associated with aggressive tumor behavior." (PMID 39200315, 2024). "Increasing concentrations of the MMP-9 inhibitor effectively abrogated the suppressive influence of melanoma-associated fibroblasts (MAFs) on PD-L1 expression in melanoma cells." (PMID 39769318, 2024). "Several studies have shown that elevated levels of MPO, MMP-9 and IL-8 are associated with poor prognosis and compromised immune response in melanoma." (PMID 38730718, 2024). "We observed a reduction in migration and invasion of both melanoma cell lines associated with reduced activity of MMP-9 and MMP-2 when treatment with GlaB and C22 was performed." (PMID 38399442, 2024). "Another study reported that high serum MMP-9 levels correlate with extensive metastases and reduced survival rates in melanoma patients, while elevated MMP-1 levels are associated with faster disease progression post-therapy initiation." (PMID 39766118, 2024). "In one study, increased levels of MMP-9 were associated with a 50% increase in metastatic potential in melanoma models." (PMID 39200315, 2024). "Other markers noted in studies that identified VM-capable glioblastoma cells were expression of VE-cadherin, MMP-2, MMP-9, and EphA2, all of which have previously been associated with VM in melanoma." (PMID 36823554, 2023). "By contrast, knockout of the TPC2 gene in CHL1 and B16-F10 primary murine melanoma cells increased invasion, with an associated increase in matrix metalloproteinase 9 (MMP-9) expression." (PMID 36046356, 2022). "Particularly, MMP-9 is the most involved in melanoma, being implicated in neoangiogenesis, ECM degradation, tumor invasion, cell migration, and formation of metastasis." (PMID 34440462, 2021). "We previously documented that loss of TNX expression accompanies MMP2 and MMP9 upregulation in melanoma tumor cells." (PMID 33782532, 2021). "In fact, different studies have identified specific ncRNAs associated with melanoma or miRNAs able to selectively target and modulate MMP-9." (PMID 34440462, 2021). "Previous study suggested that TRIM59 loss in M2 macrophages promotes melanoma migration and invasion by upregulating MMP-9 and Madcam1." (PMID 32867817, 2020). "Nevertheless, our data demonstrate that nuclear DLC1 is clinically associated with FOXK1 to promote melanoma invasion and metastasis through cooperative activation of MMP9 expression." (PMID 32214200, 2020). "Other mechanisms of MMP-9 over-expression in melanoma are mediated by neural crest associated genes, i.e., FOXD1, via the RAC1B pathway." (PMID 32392801, 2020). "In this context, several studies have tried to understand the diagnostic, prognostic and therapeutic potential of MMP-9 in melanoma patients by performing clinical trials with synthetic MMPs inhibitors." (PMID 32392801, 2020). "Specifically, through the analysis of bioinformatics data, it was possible to identify specific microRNAs (miRNAs) associated with melanoma or miRNAs able to selectively target and modulate MMP-9." (PMID 32392801, 2020). "For example, TCDD exposure of human A2058 melanoma cells induced the expression of MMP-1, MMP-2, and MMP-9, which was associated with enhanced invasive growth of melanoma cells in vitro." (PMID 31795255, 2019).
melanoma (continued). "Circulating-free DNA BRAFV600E mutation was detected in 11 out of 26 melanoma patients showing higher levels of MMP-9 compared to those with undetectable BRAFV600E mutation." (PMID 30154717, 2018). "Another recent study reports the correlation of MMP-9 hypermethylation with its overexpression in melanoma indicating novel molecular mechanisms underlying the MMPs activity and their modulatory role in melanoma aggressiveness." (PMID 30591049, 2018). "MMP-2 has been shown to enhance adhesion and migration of melanoma cells via increasing cleavage of fibronectin, and MMP-9 overexpression has been found to be associated with tumor melanoma invasion and migration." (PMID 30042328, 2018). "After the in vitro evaluations, circulating-free DNA BRAFV600E mutation and MMP-9 serum levels were evaluated in melanoma patients." (PMID 30154717, 2018). "A number of studies have showed that IL-10 reduces the synthesis level of VEGF, TNF-α, or MMP-9, which leads to a prevention of angiogenesis associated with the growth of the tumour; such as melanoma and prostate cancer." (PMID 30458011, 2018). "Among these point mutations, BRAFV600E represents the most frequent alteration observed in melanoma and many scientific evidences suggest that BRAFV600E mutation is associated with the over-expression of MMP-9 in several tumor types, including melanoma." (PMID 30154717, 2018). "IL-10 has been shown to inhibit the production of IL-1, IL-6, IL-8, TNF-α and forced expression of IL-10 suppressed VEGF and MMP-9, secreted by tumor-associated macrophages in melanoma model." (PMID 29219852, 2017). "It has been previously shown that PTTG1 can promote tumor cell invasiveness by increasing the expression of several effector molecules, including MMP-9 which has been associated with an invasive phenotype in melanoma." (PMID 29371923, 2017). "In conclusion, this study is the first to show that TRPM5 is associated with acidic pHe-signaling in Mmp9 mRNA expression in B16-BL6 melanoma cells and that pharmacological inhibition of TRPM5 successfully inhibited their spontaneous metastasis." (PMID 29108231, 2017). "For example, lncRNA SLNCR1 associates with poor melanoma survival and increases melanoma invasion via transcriptionally activating MMP9." (PMID 28935763, 2017). "In particular, we demonstrated that BSG is a novel interacting partner of TRAF6, which regulates BSG membrane recruitment, BSG-dependent MMP9 expression and melanoma cells invasiveness via K63-linked ubiquitination." (PMID 26769849, 2016). "The resulting decrease in PTEN protein was associated with enhanced expression of MMP-2 and MMP-9, two matrix proteases that are also implicated in melanoma pathogenesis." (PMID 25587717, 2015). "Fx inhibited the expression and secretion of matrix metalloproteinase-9 (MMP-9), linked to tumour invasion and migration, and also suppressed invasion of highly metastatic B16-F10 melanoma cells." (PMID 26264004, 2015). "Experimental metastasis studies in mouse models in which lung carcinoma or melanoma cells were injected into MMP9-deficient mice showed that host MMP9 promotes metastatic colonization of the lung." (PMID 24811362, 2014). "In melanoma, increased expression of MMP-2 is associated with high invasiveness and melanoma progression, while expression of MMP-9 was associated with metastasis." (PMID 25491880, 2014). "There are several reports showing different MMP expression patterns in melanoma but, to the best of our knowledge, this is the first genetic study to examine the role of polymorphisms in MMP-9 in melanoma progression and other melanoma risk factors." (PMID 17346338, 2007). "We tested seven polymorphisms within the MMP-9 gene in 1002 patients with melanoma in order to evaluate germline genetic variants and their association with progression and known risk factors of melanoma." (PMID 17346338, 2007).
melanoma (continued). "At the same time, other studies have shown that histone clipping is pro-tumorigenic; H3 clipping by Matrix Metalloproteinase 9 (MMP-9) is a consistent feature in both multiple colon cancer cell lines and melanoma cells, likely through the activation of growth-associated genes." (PMID 40381696, 2025). "Furthermore, another study demonstrated that the overexpression of MMP-2 and MMP-9 in melanoma cells is associated with increased tumor invasiveness and poor prognosis." (PMID 39200315, 2024). "In addition to their role in promoting invasion and metastasis, MMP-2 and MMP-9 have also been implicated in other aspects of melanoma progression." (PMID 37504268, 2023). "Interestingly, upregulation of MMP2 and MMP9 was linked with the depletion of nestin, a protein postulated as a melanoma stem cell marker, which was also observed in our research model." (PMID 31877948, 2019). "However, MMP-9 has been associated with the aberrant activation of MAPK pathway in melanoma, suggesting its role as prognostic indicator." (PMID 30154717, 2018). "CD44 and MMPs MMP2 and MMP9 are implicated in the progression and metastasis of melanoma." (PMID 30157785, 2018). "The present study assessed whether TRPM5, an intracellular Ca2+-dependent monovalent cation channel, is associated with acidic pHe signaling and induction of MMP-9 expression in this mouse melanoma model." (PMID 29108231, 2017). "MMP-2 and MMP-9 are linked to VM and poor prognosis in cancers of the breast, ovaries, prostate, liver, stomach and kidneys, along with GISTs, mesothelial sarcomas, rhabdomyosarcomas and melanomas." (PMID 27034014, 2017). "Over-expression of MMP2 or MMP9 is often associated with melanoma metastasis and lesions." (PMID 26769849, 2016). "Thus, we conclude that this study does not provide strong evidence for further investigation into the role of the MMP-9 variants in melanoma progression." (PMID 17346338, 2007). "PI3Kγ expression on B16F10 melanoma cells promotes metastasis to the lungs of mice suffering from melanoma caused via the injection of B16F10 cells to their tail veins through increasing the expression of MMP-9, uPA, VEGF, HIF-1α, and HIF-2α by tumor-associated macrophages (TAMs)." (PMID 32902664, 2021). "Inhibition of CTGF with a specific anti‐CTGF monoclonal antibody (FG‐3019) reduced MMP‐9 expression and significantly impeded the ability of human melanoma cells to grow in the skin." (PMID 41546170, 2026). "Compared with other immune-associated skin diseases, compelling evidence indicates aberrant MMP-9 expression in psoriasis, vitiligo, bullous pemphigoid, and melanoma." (PMID 41948343, 2026). "The creation of a fibrotic stroma ECM shield around melanoma cells facilitates MMP9-dependent PD-L1 cleavage, downregulating MHC-I expression and helping the tumor evade immune recognition." (PMID 40872475, 2025). "Of note, HH044 treatment significantly reduced the expression of EDN1, PDGFB, and MMP9, which are known to facilitate melanoma disease progression and serve as druggable targets for pharmacotherapy." (PMID 40574005, 2025). "IFN-β inhibits the production of VEGF and matrix MMP9 by neutrophils, consequently suppressing angiogenesis in melanoma." (PMID 40564191, 2025). "In canine malignant melanoma, increased MMP-2 and MMP-9 expression has similarly been associated with enhanced invasiveness, suggesting conserved mechanisms between species." (PMID 41394861, 2025). "Unexpectedly, in the trans-well co-culture model, MMP-9 expression displayed an opposite trend compared to normal human keratinocytes (NHKs) treated with melanoma-derived soluble factors (SPNs)." (PMID 40869222, 2025). "Prior studies in melanoma demonstrate that the TNF-α/NF-κB/MMP9 axis promotes early metastasis by facilitating detachment from primary tumors and systemic dissemination via vascular or lymphatic routes." (PMID 40948800, 2025).
melanoma (continued). "Consistent with previous research, our findings indicate that CXCL13 facilitates both melanoma cell invasion and metastasis while also promoting immune evasion by modulating the expression of MMP9 and PD‐L1 in tumor cells." (PMID 40692663, 2025). "Tumors with a high MMP-9 expression (e.g., breast, glioblastoma, colorectal, melanoma, and lung cancers) are particularly amenable to targeted therapies." (PMID 40284474, 2025). "For anti-metastasis, IVIG reduced melanoma and sarcoma spread in experimental models by boosting IL-12 and NK cell activity and suppressing MMP-9, also demonstrating anti-angiogenic properties that hinder metastasis development." (PMID 40630912, 2025). "For example, TAMs have been shown to secrete matrix metalloproteinases (MMPs) such as MMP-9, which degrade the extracellular matrix and allow melanoma cells to invade surrounding tissues." (PMID 39200315, 2024). "The role of MMP-9 in promoting melanoma development was demonstrated by facilitating H3 N-terminal tail cleavage (H3NT) proteolysis within the promoter and coding regions of pro-melanomagenic genes, consequently enhancing their expression." (PMID 39409117, 2024). "MMP9 is involved in the melanogenesis pathway and is considered a promising biomarker and therapeutic target for managing melanoma patients." (PMID 38511062, 2024). "Intriguingly, these results extend beyond the laboratory setting, as kaempferol has been shown to obstruct lung metastasis of B16F10 murine melanoma cells while simultaneously reducing the expression of MMP-9 in vivo." (PMID 38939095, 2024). "MMP-2 and MMP-9 are overexpressed in melanoma cells and positively correlated with highly metastatic tumor behavior, while their endogenous inhibitors, TIMP-1 and -2, are down-regulated in melanoma cells, exhibiting aggressive potential." (PMID 38247872, 2024). "BMP4 is reportedly involved in human malignant melanoma and alters biological functions, and inhibits MMP9 expression in cancer cells." (PMID 38511062, 2024). "Utilizing shRNA to downregulate LAMP1 in B16F10 mouse melanoma cells can attenuate the induction of matrix metalloproteinase (MMP9) expression by the p38 MAPK signaling pathway activated by galectin-3 and polyN-acetyllactosamine (polyLacNAc)." (PMID 39669571, 2024). "Next, as metalloprotease activity is related to melanoma invasion, we observed MMP-9 and MMP-2 in SK-MEL-28 by zymogram assay." (PMID 38399442, 2024). "Specifically, MMP-9 expression was significantly higher in more aggressive melanoma subtypes, correlating with a 50% increase in metastatic potential." (PMID 39200315, 2024). "Genistein also induced a concentration-dependent reduction in the secretion and expression of MMP-2 and MMP-9 in melanoma 518 A2 cells, with a stronger effect than two other flavones: chrysin and apigenin." (PMID 39335164, 2024). "Instead, in the context of melanoma, excessive production of MMP1, MMP2, MMP9, and MMP19 has been frequently associated with invasion behavior of tumor cells." (PMID 38473275, 2024). "Luteolin downregulates MMP-2 and MMP-9 expression via the PI3K/AKT pathway to decrease melanoma cell growth and induce apoptosis." (PMID 38398617, 2024). "Macrophages also facilitate melanoma progression, as evidenced by their increased density at the invasive front of melanoma lesions, and facilitate metastasis through the secretion of metalloproteinases like MMP-9, which remodel the ECM." (PMID 39337605, 2024). "Roomi and colleagues assessed the role of EGCG in the regulation of MMP-2 and MMP-9 in human melanoma A-2058 cells using a gelatinase zymography assay and densitometry analysis." (PMID 39335164, 2024). "eUb reduces apoptosis and promotes lung metastasis, as well as tumor progression of B16 melanoma in mice, which is related to increased matrix metalloproteinase-9 (MMP9) and vascular endothelial growth factor (VEGF) production." (PMID 38399400, 2024).